RAF1 (Raf-1 proto-oncogene, serine/threonine kinase)
Description:
Serine/threonine-protein kinase that acts as a regulatory link between the membrane-associated Ras GTPases and the MAPK/ERK cascade, and this critical regulatory link functions as a switch determining cell fate decisions including proliferation, differentiation, apoptosis, survival and oncogenic transformation. RAF1 activation initiates a mitogen-activated protein kinase (MAPK) cascade that comprises a sequential phosphorylation of the dual-specific MAPK kinases (MAP2K1/MEK1 and MAP2K2/MEK2) and the extracellular signal-regulated kinases (MAPK3/ERK1 and MAPK1/ERK2). The phosphorylated form of RAF1 (on residues Ser-338 and Ser-339, by PAK1) phosphorylates BAD/Bcl2-antagonist of cell death at 'Ser-75'. Phosphorylates adenylyl cyclases: ADCY2, ADCY5 and ADCY6, resulting in their activation. Phosphorylates PPP1R12A resulting in inhibition of the phosphatase activity. Phosphorylates TNNT2/cardiac muscle troponin T. Can promote NF-kB activation and inhibit signal transducers involved in motility (ROCK2), apoptosis (MAP3K5/ASK1 and STK3/MST2), proliferation and angiogenesis (RB1). Can protect cells from apoptosis also by translocating to the mitochondria where it binds BCL2 and displaces BAD/Bcl2-antagonist of cell death. Regulates Rho signaling and migration, and is required for normal wound healing. Plays a role in the oncogenic transformation of epithelial cells via repression of the TJ protein, occludin (OCLN) by inducing the up-regulation of a transcriptional repressor SNAI2/SLUG, which induces down-regulation of OCLN. Restricts caspase activation in response to selected stimuli, notably Fas stimulation, pathogen-mediated macrophage apoptosis, and erythroid differentiation.
Synonyms: cRaf; Raf-1; c-Raf; CMD1NN; NS5
Tractability: Small molecule: an approved drug acts on it; a structure with a bound ligand is known; a high-quality ligand is known; it has a high-quality binding pocket; it belongs to a druggable protein family. Antibody: its Gene Ontology location is reachable by antibodies, with high confidence; UniProt places it where antibodies can reach, with medium confidence; the Human Protein Atlas places it where antibodies can reach. PROTAC: ubiquitination databases record sites on it; its protein half-life has been measured; a small molecule that binds it is known.
Target class: Kinase; Enzyme; TKL protein kinase RAF family; Protein Kinase; TKL protein kinase group
Chemical probes: PD081646, PD134562, PD134563, PD134564, PD134565, PD134566, PD134567, PD134568, PD134569, PD134570, PD134571, SB-590885
Safety:
Unwanted effects reported when the protein is acted on. In parentheses: how it was acted on, where the effect was seen, and who reports it.
heart disease (cardiovascular system; source: Force et al. (2011))
Gene: Protein-coding gene on chromosome 3 (12,582,101 to 12,664,201, reverse strand). Ensembl gene ENSG00000132155.
Subcellular location: Cytoplasm; Cell membrane; Mitochondrion; Nucleus
Subcellular location (Human Protein Atlas): Cytosol; Plasma membrane
Pathways (Reactome):
Disease: Gain-of-function MRAS complexes activate RAF signaling; Paradoxical activation of RAF signaling by kinase inactive BRAF; SHOC2 M1731 mutant abolishes MRAS complex function; Signaling by BRAF and RAF1 fusions; Signaling by RAF1 mutants; Signaling by high-kinase activity BRAF mutants; Signaling by moderate kinase activity BRAF mutants; Signaling downstream of RAS mutants
Signal Transduction: MAP2K and MAPK activation; Negative feedback regulation of MAPK pathway; Negative regulation of MAPK pathway; RAF activation
Immune System: CD209 (DC-SIGN) signaling; IFNG signaling activates MAPKs; Rap1 signalling
Hemostasis: GP1b-IX-V activation signalling
Transport of small molecules: Stimuli-sensing channels
Gene Ontology:
Molecular function: adenylate cyclase activator activity; enzyme binding; identical protein binding; protein binding; protein kinase activity; protein serine kinase activity; protein serine/threonine kinase activity; small GTPase binding; MAP kinase kinase kinase activity; ATP binding
Biological process: interleukin-8-mediated signaling pathway; MAPK cascade; negative regulation of apoptotic process; negative regulation of cell population proliferation; negative regulation of protein-containing complex assembly; positive regulation of MAPK cascade; positive regulation of peptidyl-serine phosphorylation; apoptotic process; protein phosphorylation; regulation of apoptotic process; regulation of cell differentiation; regulation of Rho protein signal transduction; signal transduction; type II interferon-mediated signaling pathway; wound healing; ERBB signaling pathway; ERBB2-ERBB3 signaling pathway; insulin receptor signaling pathway; insulin-like growth factor receptor signaling pathway; myelination; neuromuscular junction development; Schwann cell development
Cellular component: cytoplasm; cytosol; Golgi apparatus; plasma membrane; serine/threonine protein kinase complex; mitochondrial outer membrane; mitochondrion; nucleus; pseudopodium
Genetic constraint (gnomAD): Loss-of-function variants: 19 observed, 78.98 expected, observed/expected ratio (o/e) 0.24, 90% interval 0.17 to 0.35. The upper end of that interval is the gene's LOEUF score, 0.35, which puts it in group 1 of 6, group 1 being the genes least tolerant of losing a copy. Missense variants: 576 observed, 849.62 expected, observed/expected ratio (o/e) 0.68, 90% interval 0.63 to 0.73. Synonymous variants: 292 observed, 304.21 expected, observed/expected ratio (o/e) 0.96, 90% interval 0.87 to 1.06.
Gene-disease validity (ClinGen):
ClinGen rates the evidence that RAF1 causes each of these diseases.
Noonan syndrome (autosomal dominant): Definitive. Noonan Syndrome (NS) is characterized by short stature, typical facial dysmorphism and congenital heart defects.
Noonan syndrome with multiple lentigines (autosomal dominant): Limited. A rare multisystem genetic disorder characterized by lentigines, hypertrophic cardiomyopathy, short stature, pectus deformity, and dysmorphic facial features.
cardiofaciocutaneous syndrome (autosomal dominant): Disputed. Cardiofaciocutaneous (CFC) syndrome is a RASopathy characterized by craniofacial dysmorphology, congenital heart disease, dermatological abnormalities (most commonly hyperkeratotic skin and sparse, curly hair), growth retardation and intellectual disability.
Costello syndrome (autosomal dominant): Disputed. Costello syndrome (CS) is a rare multisystemic disorder characterized by failure to thrive, short stature, developmental delay or intellectual disability, joint laxity, soft skin, and distinctive facial features.
Cancer hallmarks: angiogenesis (promotes); invasion and metastasis (promotes); proliferative signalling (promotes); escaping programmed cell death (promotes)
Homologues: Orthologues: macaque RAF1 (100% identical), chimpanzee RAF1 (99% identical), pig RAF1 (99% identical), dog RAF1 (99% identical), guinea pig RAF1 (98% identical), rat Raf1 (98% identical), mouse Raf1 (98% identical), rabbit RAF1 (93% identical), tropical clawed frog raf1 (87% identical), zebrafish raf1b (77% identical), zebrafish raf1a (75% identical). Paralogues in human: ARAF (59% identical), BRAF (57% identical), KSR2 (21% identical), TNNI3K (21% identical), MAP3K9 (20% identical), KSR1 (20% identical), MAP3K11 (19% identical), MAP3K21 (19% identical), MAP3K10 (18% identical), LIMK2 (17% identical), LRRK2 (17% identical), LIMK1 (17% identical), and 11 more.
Diseases named in the same sentence as RAF1 in open-access papers:
RAF1 is named in the same sentence as 316 diseases in open-access papers, as found by Europe PMC text mining. Sharing a sentence is not in itself a finding about the gene and the disease. The quoted sentences say what the papers report.
melanoma (118 papers, 2004 to 2026). A malignant, usually aggressive tumor composed of atypical, neoplastic melanocytes. "Area A and the melanoma in situ instead harbored amplifications of RAF1 (encoding CRAF) as the likely MAP-kinase pathway driver, and this RAF1 amplification was absent from all other areas." (PMID 39034322, 2024). "In a cohort study comprised of 7119 melanoma patients, 40 cases (0.6%) were identified with activated RAF1 structural variants accompanied by mutations in TERTp and CDKN2A." (PMID 38111008, 2023). "This is the case, for instance, in NRAS-mutated melanoma, in which RAF1 and BRAF compensate for each other, and ARAF compensates for the loss of both other isoforms in a mechanism that is still ERK-dependent." (PMID 37020037, 2023). "TMB-H was also observed in RAF1 fusion-positive melanomas (n = 3), with pathogenic mutations identified in two or more genes per tumor." (PMID 35326655, 2022). "In cases of urothelial cancer, causal relationships between TIL and most of these genes remain sparse in the current literature, however, one study found that RAF1 fusions were associated with low TIL presence in melanoma cases." (PMID 34114376, 2021). "The list comprises of several well-known melanoma-associated-oncogenes including RAF1, AURKA and SRC along with putative novel oncogenes." (PMID 26558755, 2015). "This contention is supported by the recent observation that sorafenib administration is associated with increased RAF-1 phosphorylation at Ser338 in human melanoma and other tumour cell types." (PMID 16880785, 2006). "To investigate this distinctive group of melanomas, we searched for melanomas with activating structural variants in RAF1, utilizing our case archive of clinical samples with comprehensive genomic profiling (CGP) by a hybrid capture-based DNA sequencing platform." (PMID 32123303, 2020). "Since 3 of the 6 samples that possessed RAF1 S259F were melanoma, this variant may contribute to melanoma development." (PMID 30709382, 2019). "NF1-mutant melanomas in our cohort were enriched for SV events affecting SPRED1 and RAF1, the latter of which has been implicated in activating fusion events in cutaneous melanoma and was observed to be enriched in TWT tumors." (PMID 38758740, 2024). "RAF1 and BRAF mutations had a higher prevalence in HRASmt melanoma and UC, respectively, whereas NRAS mutations were more prevalent in HRASwt melanoma." (PMID 38672653, 2024). "Other reported melanocytic tumors involving fusions of RAF1 include malignant melanoma, BAP1-inactivating melanocytoma, and congenital naevi." (PMID 38390852, 2024). "Mutations in RAF1 are extremely rare; however, overexpression of CRAF is correlated with disease progression in a subset of human cancers, including melanoma, non-small cell lung cancer (NSCLC), and hepatocellular carcinoma." (PMID 38111008, 2023). "The percentage of patients with RAF1 aberrations was the highest in those with bladder cancer (11.5%), followed by ampulla of Vater (AoV) cancer (5.3%), melanoma (3.0%), gallbladder (GB) cancer (2.6%), and gastric cancer (2.3%)." (PMID 38137485, 2023). "Although melanomas with RAF1 fusions are seldom observed (less than 1%), clinical sample analyses have consistently shown that melanomas harboring RAF1 fusions exhibit wide-type status for BRAF, RAS, and NF1." (PMID 38111008, 2023).
melanoma (continued). "A relatively high incidence of RAF1 gene rearrangements of 14.3–18.5% has been reported in pancreatic acinar cell carcinomas and at a frequency of 0.6% (40/7119) in melanoma patients." (PMID 38137485, 2023). "RAF1 fusions are actionable molecular events that have been reported in various tumor types, including melanoma, invasive ductal carcinoma, and lung adenocarcinoma." (PMID 36033527, 2022). "The RAF1 fusion activated by the RAF1 (CRAF) gene has been reported in a few melanomas and pediatric low-grade gliomas; in some cases, MEK inhibitors have been reported to be effective against RAF1 fusions." (PMID 36033527, 2022). "In our series, however, activating RAF1-fusion melanoma was almost entirely triple wild type, cutaneous, and UV driven." (PMID 32123303, 2020). "In this study, we present the first series of activating RAF1-fusion melanomas with clinical–pathologic correlation, detailed descriptions of several new fusion variants, and a thorough characterization of accompanying mutations." (PMID 32123303, 2020). "In one study seeking therapeutically targetable gene fusions in multiple cancer types, FISH for BRAF and RAF1 performed on 131 melanomas identified one BRAF rearrangement and one RAF1 rearrangement." (PMID 32123303, 2020). "RAF1 fusion was detected in 4 cases (GC, melanoma, STS, and pancreatic cancer), BRAF fusion in 2 cases (BTC and STS), ALK fusion in 2 cases (CRC and BTC), ROS1 fusion in 1 case (CRC), and EGFR fusion in 1 case (CRC) with diverse counterparts." (PMID 32411236, 2020). "The RAF1 kinase mRNA was an interesting candidate as it fulfilled these criteria both as a target of miR-7-5p, as described in melanoma cells, and as a regulator of autophagy, as previously reported." (PMID 33066037, 2020). "Activating RAF1 fusions represent a significant subset of triple wild-type melanoma (2.1% of all triple wild-type melanoma)." (PMID 32123303, 2020). "A more recent study of kinase fusions across large numbers of various malignancies found four cases of RAF1 fusion out of 397 melanomas." (PMID 32123303, 2020). "Inhibitors of V600E-B-RAF and RAF1 (C-RAF) kinases have been reported as antiproliferative agents against melanoma." (PMID 32962435, 2020). "Additional studies will be needed to correlate the finding of activating RAF1 fusions in melanoma with prognostic data and treatment outcomes." (PMID 32123303, 2020). "A whole-genome study of 183 melanomas found RAF1 fusions in two melanomas (with partners CDH3 and GOLGA4): one triple wild type and one with an NF1 comutation." (PMID 32123303, 2020). "We note that the median age of 62 years for RAF1-fusion melanomas in this study is significantly older than that reported in prior melanocytic tumors with gene fusions, which tend toward pediatric and young adult patients." (PMID 32123303, 2020). "One report described a melanoma with GOLGA4 fused to exons 8–17 of RAF1, retaining the RAF1 kinase domains, and with accompanying mutations in CTNNB1 and CDKN2A." (PMID 32123303, 2020). "Prognostic data will also enable the comparison of RAF1-fused melanomas by comutations, such as TERTp, which has been shown to be an important prognostic marker for spitzoid melanocytic neoplasms." (PMID 32123303, 2020). "Among patients with activating RAF1-rearranged melanomas, the ages ranged from 34 to 86 years, with a median of 62 years." (PMID 32123303, 2020). "Other mutations frequently associated with NF1 loss in melanoma occur in PTPN11, SOS1, RAF1, SPRED1 and other genes." (PMID 32605090, 2020). "Treatment with 2HF at 50 or 100 μM reduced the expression levels of TNFα, RAF1, and p-PDGFR-β proteins, each of which has been implicated in causing treatment resistance in melanoma." (PMID 31615091, 2019). "For instance, ORAI1-mediated Ca2+ entry stimulated human melanoma cell migration by recruiting Ca2+/Calmodulin-dependent kinase II (CaMKII) to induce Raf-1 phosphorylation, thereby activating the ERK pathway." (PMID 30754672, 2019).
melanoma (continued). "Although BRAF has gained more attention in melanoma, RAF1 plays an important role in MAPK signaling." (PMID 30709382, 2019). "Evidence for the role of Raf dimerisation in drug resistance was provided in co-immunoprecipitation experiments, which showed that MEK1/2 inhibition increased the formation of Raf-1/B-Raf dimers in melanoma cells." (PMID 27342992, 2016). "Activated SOCE is also associated with activation of ERK signaling and is inhibited by calmodulin kinase II (CaMKII) and Raf-1 in malignant melanoma." (PMID 27472555, 2016). "Another study found rearrangements in gastric, prostate cancer and melanoma that involve again fusions containing BRAF or RAF1 segments." (PMID 25473895, 2015). "In some MEK inhibitor-resistant melanoma cells which contained either the G469E or D594G mutant BRAF alleles, activation of Raf-1 by the mutant B-Raf proteins was observed to confer resistance to MEK inhibitors." (PMID 23085539, 2012). "We demonstrate that, paradoxically, whereas PLX4032 inhibited extracellular signal-regulated kinase (ERK) in BRAFV600E/K-mutants, it induced the pathway in BRAFWT melanoma cells via activation of RAF1." (PMID 20149136, 2010). "In these reports, the investigators also observed that selective BRAF inhibitors, such as PLX4720, 885-A and GDC-0879 stimulated MEK–ERK signaling in BRAF wild-type melanoma and carcinoma cells via RAF1 activation." (PMID 20149136, 2010). "We demonstrated that while PLX4032 inhibited ERK1/2 in BRAFV600E/K, it activated this signaling pathway in BRAFWT melanoma cells via stimulation of RAF1 in a RAS-independent manner." (PMID 20149136, 2010). "Moreover, researchers have identified single amino acid substitutions (p.S257P, p.P261T, p.G361A, p.E478K) within RAF1 in melanoma cell lines resistant to RAF inhibitors." (PMID 38111008, 2023). "Together, these results suggest BRAF and RAF1 fusions are drivers of MAPK signaling in melanoma." (PMID 35326655, 2022). "In addition, mutation of functional NF1 is associated with BRAFi resistance in melanoma and mutations in the PTPN11, SOS1, RAF1 and SPRED1 genes frequently co-occur with NF1 loss." (PMID 33807778, 2021). "The literature on melanoma with rearrangements in kinase genes other than RAF1 is extensive." (PMID 32123303, 2020). "Activating RAF1 fusions were present in 2.1% of triple wild-type melanomas overall (39/1882)." (PMID 32123303, 2020). "In RAS-mutated melanoma, PKA regulates the MAPK/ERK signaling by switching BRAF to RAF-1 signaling." (PMID 33396632, 2020). "Melanomas with RAF1 fusions have been rarely reported, mostly in clinical literature." (PMID 32123303, 2020). "Prior histopathologic descriptions of activating RAF1-fusion melanomas are limited." (PMID 32123303, 2020). "Importantly, we have recently described experiments that functionally validated the role of four of these candidates (VAV1, MCF2, BRAF, RAF1) in driving vemurafenib resistance in human melanoma cell lines." (PMID 31208320, 2019). "We therefore went on to screen the drug effect on a cohort of 30 patient-derived short-term cultures of melanoma cell lines carrying BRAFV600E/K, NRASQ61K/L/R, NF1null, RAC1P129S, RAF1 or BRAF fusion proteins, as well as other mutations identified by exome-capture sequencing." (PMID 31040916, 2019). "Furthermore, on the basis of analyses of somatic co-mutation patterns in the TCGA data sets (cBio Portal for Cancer Genomics), 9.6% of melanomas with NF1 mutations also have mutations in BRAF, NRAS or RAF1." (PMID 28637487, 2017). "In addition, all 26 NF1 mutant BRAF-RAS wild-type melanomas carried mutations in other known RASopathy genes, including RASA2, PTPN11, SOS1, RAF1 and SPRED1." (PMID 28637487, 2017).